MT-TH (mitochondrially encoded tRNA-His (CAU/C))
Synonyms: trnH; formerly MTTH
Gene: Mitochondrial transfer RNA gene on chromosome MT (12,138 to 12,206, forward strand). Ensembl gene ENSG00000210176.
Gene Ontology:
Molecular function: triplet codon-amino acid adaptor activity
Biological process: translation
Gene-disease validity (ClinGen):
ClinGen rates the evidence that MT-TH causes each of these diseases.
mitochondrial disease (mitochondrial): Definitive.
Diseases named in the same sentence as MT-TH in open-access papers:
MT-TH is named in the same sentence as 3 diseases in open-access papers, as found by Europe PMC text mining. Sharing a sentence is not in itself a finding about the gene and the disease.
MT-TH shares sentences with these, for which no sentence is quoted: dengue (1 paper); malaria (1); viral infections (1).